IL11 (interleukin 11)
Diseases named in the same sentence as IL11 in open-access papers (continued):
Sharing a sentence is not in itself a finding about the gene and the disease.
preeclampsia (4 papers, 2019 to 2023). Preeclampsia is a hypertensive disorder of pregnancy that is characterized by new-onset hypertension with proteinuria presenting after 20 weeks of gestation, and depending on mild or severe forms may initially present with severe headache, visual disturbances, and hyperreflexia. "Demonstrating a causal role for IL11 in the etiology of early-onset preeclampsia, we have shown that IL11 inhibits human 1st trimester primary trophoblast cell outgrowth and invasion." (PMID 37292200, 2023). "In conclusion, here we demonstrate that IL11 activated the placental inflammasome, causing pyroptosis in human placental villus and the features of preeclampsia in a murine model." (PMID 37292200, 2023). "However, the precise mechanism by which IL11 causes placental damage and induces preeclampsia is unknown, although IL11 activates many pathways known to be altered in preeclampsia." (PMID 37292200, 2023). "IL11 is elevated in maternal serum, placenta, and decidua from pregnancies with early-onset preeclampsia." (PMID 37292200, 2023). "We previously showed that IL11 administration to pregnant mice induced features of preeclampsia including elevated blood pressure and impaired placentation." (PMID 37292200, 2023). "We previously reported enhanced decidual IL-6 and IL-11 levels at the maternal-fetal interface with significantly higher peri-membranous IL-6 immunostaining in adjacent interstitial trophoblasts in preeclampsia (PE) vs. gestational age (GA)-matched controls." (PMID 35837332, 2022). "Recently IL-11, a member of the IL-6 family also known as adipogenesis inhibitory factor (AGIF), has been found by others to be upregulated in PE and leads to inflammation and preeclampsia-like features in mice." (PMID 31905805, 2019). "Inhibition of ASC/NLRP3 inflammasome activity could prevent IL11-induced inflammation and fibrosis in various disease states including preeclampsia." (PMID 37292200, 2023). "Given that IL11 activates the human placental inflammasome, we investigated whether IL11 acts via inflammasomes to drive preeclampsia in mice." (PMID 37292200, 2023). "We aimed to determine the effects of IL11 on inflammasome activation in human and mouse placenta and whether loss of NLRP3/ASC-inflammasome activity could prevent IL11-induced preeclampsia." (PMID 37292200, 2023). "Therapeutic inhibition of the ASC or NLRP3 inflammasome in women with elevated serum IL11 in early pregnancy could prevent IL11-induced placental inflammation and subsequent preeclampsia." (PMID 37292200, 2023). "There is emerging evidence for elevated placental inflammasome activation in early-onset preeclampsia; thus, we hypothesized that IL11 would activate placental inflammasomes resulting in cleaved IL1β, pyroptosis, and initiation of the cascade of events leading to preeclampsia." (PMID 37292200, 2023). "However, the mechanism by which IL11 drives preeclampsia is unknown." (PMID 37292200, 2023). "We also found that IL11 treatment increased ASC immunostaining in the stroma of the human placental villus, the location of fibrosis in preeclampsia." (PMID 37292200, 2023).
psoriasis (4 papers, 2017 to 2024). An autoimmune condition characterized by red, well-delineated plaques with silvery scales that are usually on the extensor surfaces and scalp. "As already reported by other studies, the levels of anti-inflammatory molecules like IL-10 and IL-11 reduce in some inflammatory conditions like infection and psoriasis." (PMID 31878248, 2019). "It has been speculated that IL-11 may play an important role in the resolution of skin inflammation in patients with psoriasis and plays an important role in tissue remodeling." (PMID 39408993, 2024).
pulmonary hypertension (4 papers, 2022 to 2023). Increased pressure within the pulmonary circulation due to lung or heart disorder. "IL11 also induces VSMC senescence that is associated with pulmonary hypertension and fibrosis." (PMID 38054591, 2023). "We propose that IL11-driven EndMT directly or indirectly contributes to the perivascular fibrosis demonstrated here and in pulmonary hypertension." (PMID 37629170, 2023). "Intriguingly, IL11 was found to play a role in EndMT in the pulmonary arteries in the setting of idiopathic pulmonary fibrosis-related pulmonary hypertension." (PMID 37629170, 2023). "IL11 causes VSMC proliferation and vascular fibrosis of the pulmonary vasculature in the context of pulmonary hypertension." (PMID 38054591, 2023). "This work introduce IL-11 and IL-11Rα as a drivers of pulmonary hypertension potentially druggable to reduce pulmonary artery remodeling." (PMID 36376885, 2022). "Transiently transfection of siRNA-IL-11 reduced pulmonary artery remodeling and pulmonary hypertension as well as the number of positive Tie2-GFP cells in lung parenchyma which confirm the role of IL-11 on in vivo EnMT." (PMID 36376885, 2022).
renal failure (4 papers, 2022 to 2024). "Here, the authors show that in kidney failure, genetic or pharmacologic inhibition of IL11 releases the brake on regeneration, reverses tissue damage and restores kidney function." (PMID 36470928, 2022).
squamous cell carcinoma (4 papers, 2022 to 2024). A carcinoma arising from squamous epithelial cells. "Necrotic lysates of the human squamous carcinoma cell lines HSC2 and TR146, as well as of gingival fibroblasts, however, caused a robust increase in IL11 expression in the gingival fibroblasts." (PMID 37892923, 2023). "Interestingly, BALF IL11 expression was not increased in squamous cell carcinoma (SCC), a type of NSCLC of epithelial origin, which may suggest cell type-selective IL11 expression in NSCLC." (PMID 35883698, 2022).
adenoma (3 papers, 2020 to 2024). A neoplasm arising from the epithelium. "IL-11+ cells were scarce in normal colonic tissues but were numerous in adenomas and in early and advanced CRC tissues." (PMID 33863879, 2021). "Indeed, our results expand on previous observations that excessive STAT3 activity in the gastric epithelium mediated by IL-11 triggers the formation of non-invasive adenomas in gp130F/F mice." (PMID 39128004, 2024). "However, while aberrant KRAS activation alone induced gastric metaplasia, the formation of adenoma was dependent on the additional activation of gp130, mainly through interleukin 11 (IL-11)." (PMID 32698506, 2020).
anaplastic thyroid carcinoma (3 papers, 2016 to 2019). "In hypoxic condition, secretion of IL-11, is induced in anaplastic thyroid carcinoma cells and IL-11 activates PI3K/AKT/glycogen synthase kinase 3 β (GSK3β) and results in EMT phenotype." (PMID 28718842, 2017). "IL11 has been reported to play an oncogenic role in anaplastic thyroid carcinoma." (PMID 30661062, 2019).
anemia (3 papers, 2014 to 2025). A reduction in the number of red blood cells, the amount of hemoglobin, and/or the volume of packed red blood cells. "On OAR14:62,954,922 was found the SNP rs420711470, which was found to be associated with ALL and LPL, and close to this SNP is the IL11 (interleukin 11) gene, another gene with hematopoietic effects and potential therapeutic value in anemia conditions." (PMID 40678382, 2025).
atrial fibrillation (3 papers, 2023 to 2025). A disorder characterized by an electrocardiographic finding of a supraventricular arrhythmia characterized by the replacement of consistent P waves by rapid oscillations or fibrillatory waves that vary in size, shape and timing and are accompanied by an irregular ventricular response. "The role and the underlying mechanism of IL-11 in atrial fibrillation were examined by immunofluorescence, measurements of reactive oxygen species (ROS) and mitochondrial membrane potential (MMP), and western blotting assays." (PMID 40092733, 2025). "IL11 levels are also elevated in patients with atrial fibrillation: IL11 causes atrial fibrosis in mice and sensitises the atrium to fibrillation in old rats." (PMID 38054591, 2023). "Elevated IL-11 levels have been observed in atrial fibrillation and are correlated with serum markers of fibrosis, making IL-11 a potential therapeutic target for atrial fibrosis." (PMID 40092733, 2025). "IL-11’s role in atrial fibrillation pathogenesis, such as oxidative stress, mitochondrial dysfunction, and autophagy, was explored in Ang-II-induced atrial fibroblasts." (PMID 40092733, 2025). "Animal models, such as mice treated with Ang-II to induce atrial fibrillation, could be used to investigate the role of IL-11 in oxidative stress, mitochondrial dysfunction, and autophagy." (PMID 40092733, 2025). "The cardiac side effects associated with IL11 include arrhythmias (notably atrial fibrillation and flutter) that we did not study here." (PMID 39383190, 2024). "In addition, the role of IL-11 in atrial fibrillation should be verified in vivo." (PMID 40092733, 2025). "However, in atrial fibrillation, IL-11 mechanisms remain unclear." (PMID 40092733, 2025).
Cachexia (3 papers, 2015 to 2019). Severe weight loss, wasting of muscle, loss of appetite, and general debility related to a chronic disease. "We know also that other mediators belonging to the IL-6 superfamily, including IL-11 and OSM are present in the serum of animals with burn-induced cachexia and can activate the STAT3 signaling system in muscle." (PMID 31447786, 2019). "IL-6 family cytokines other than LIF, which include IL-6, IL-11, and CNTF, were also reported as cachexia-inducing factors." (PMID 30410674, 2018).
chronic heart failure (3 papers, 2019 to 2025). "In contrast, increased IL-11 levels in patients with chronic heart failure were reported to correlate with cardiac events." (PMID 34516874, 2021).
colorectal tumor (3 papers, 2010 to 2021). "One month following reconstitution, Il11-Egfp BM chimeric mice were treated with AOM/DSS to induce colorectal tumors." (PMID 33863879, 2021). "Repeated injection of IL-11 results in an increase in the number and size of colorectal tumors in AOM/DSS-treated mice." (PMID 33863879, 2021). "Furthermore, IL11 and IL11Rα expression correlate with invasion and proliferation in human gastric and colorectal tumours." (PMID 20553623, 2010).
diabetes mellitus type 2 (3 papers, 2021 to 2024). "IL-11 is another chronic inflammatory biomarker in patients with type 2 diabetes." (PMID 38164478, 2024). "The increase in IL-11 levels is associated with decreased BAX protein production in obese patients with and without type 2 diabetes." (PMID 33579000, 2021).
fatty liver disease (3 papers, 2015 to 2025). A reversible condition wherein large vacuoles of triglyceride fat accumulate in liver cells via the process of steatosis. "Restoration of IL11 cis-signaling in KO mice using mbIl11ra1 recapitulated hepatic steatosis and inflammation that was evident from gross morphology to molecular patterns of gene expression and signaling." (PMID 33397952, 2021).
Glucose intolerance (3 papers, 2012 to 2023). Glucose intolerance (GI) can be defined as dysglycemia that comprises both prediabetes and diabetes. "Recent studies have shown that systemic and osteoblast/osteocyte-specific IL-11 deficiency leads to reduced bone mass and formation, but also adiposity, glucose intolerance, and insulin resistance." (PMID 37199584, 2023). "Moreover, systemic and osteoblast/osteocyte-specific IL-11 deficiencies led to the reduced bone mass and bone formation in response to mechanical loading, as well as increased adiposity, glucose intolerance, and insulin resistance." (PMID 37199584, 2023). "In addition, IL-11-/- mice exhibited glucose intolerance, insulin resistance, fatty liver, and inflammatory infiltration in adipose tissue." (PMID 37199584, 2023). "Unexpectedly, IL-11−/− mice have increased systemic adiposity and glucose intolerance." (PMID 36424386, 2022).
hematoma (3 papers, 2020 to 2025). A hematoma is a collection of blood from a vascular structure into an extravascular space. "Hematoma components, oxidative stress, and inflammatory microenvironments robustly induce IL11." (PMID 41487426, 2025). "Translating these findings to ICH, future prospective clinical studies are imperative to determine whether peripheral or central IL-11 levels can serve as a reliable biomarker for predicting hematoma expansion, functional outcome, or guiding targeted anti-inflammatory therapy." (PMID 41487426, 2025). "Clinical studies have reported associations between serum inflammatory markers in the acute phase of ICH, mainly CCL2, CXCL10, IL-6, IL-11, CRP, fibrinogen, and CSF cytokines with hematoma expansion and early neurological decline." (PMID 34439789, 2021).
Immunodeficiency (3 papers, 2017 to 2024). Failure of the immune system to protect the body adequately from infection, due to the absence or insufficiency of some component process or substance. "Here, we identify a patient with a causative homozygous mutation in IL6ST, encoding the human cytokine receptor subunit GP130, presenting with immunodeficiency and skeletal abnormalities including craniosynostosis, and demonstrate associated defects in IL-6, IL-11, IL-27, and OSM signaling." (PMID 28747427, 2017).
interstitial lung disease (3 papers, 2023 to 2024). A diverse group of lung diseases that affect the lung parenchyma. "IL11 is similarly expressed by KRT8+ alveolar epithelial cells lining fibrotic lesions in a mouse model of interstitial lung disease." (PMID 39358385, 2024). "We analyzed single cell RNA sequencing datasets of human interstitial lung disease and found the profibrotic Interleukin-11 (IL11) cytokine to be highly and specifically expressed in aberrant KRT8+ basaloid cells." (PMID 39358385, 2024). "IL-11 has recently been recognized as a TGF-β-responsive profibrotic cytokine and was shown to be highly upregulated in dermal fibroblasts from SSc skin and in pulmonary fibroblasts from patients suffering from interstitial lung disease associated with SSc." (PMID 36810081, 2023). "IL11 was first appreciated in SSc as the most up-regulated gene in pulmonary fibroblasts from patients with SSc interstitial lung disease (SSc-ILD)." (PMID 38054591, 2023).
intrahepatic cholangiocarcinoma (3 papers, 2022 to 2025). A carcinoma that arises from the intrahepatic bile duct epithelium in any site of the intrahepatic biliary tree. "Studies have shown that co-cultured TANs and TAM can greatly secrete OSM and IL-11, which promotes the proliferation and invasion of intrahepatic cholangiocarcinoma (ICC) cells." (PMID 35874739, 2022). "In terms of mechanism, OSM (oncostatin M), which is preferentially expressed by TANs, and IL-11, which is preferentially expressed by TAMs, jointly activate STAT3 signaling in ICC (intrahepatic cholangiocarcinoma) cells, thus achieving the tumor promoting effect." (PMID 38279145, 2024).
ischemia (3 papers, 2022 to 2025). A hypoperfusion of the BLOOD through an organ or tissue caused by a PATHOLOGIC CONSTRICTION or obstruction of its BLOOD VESSELS, or an absence of BLOOD CIRCULATION. "We used IL11 siRNA or an IL11 supplement to investigate the regulatory mechanism of OGD in promoting fibroblast senescence through IL11, which will provide a theoretical basis for the intervention of ischemia-related aging diseases." (PMID 36292942, 2022).
Marfan syndrome (3 papers, 2023 to 2024). A disorder of the connective tissue. "In a mouse model of Marfan syndrome, anti-IL11 therapy reduced aortic dilation and emphysema of the lungs." (PMID 38054591, 2023). "In a mouse model of Marfan syndrome, which is characterised by elevated TGFβ activity due to LOF mutations in fibrillin-1, IL11 levels are increased and anti-IL11 therapy reduces aortic inflammation, matrix remodelling and dilatation." (PMID 38054591, 2023). "In Marfan Syndrome, IL11 is up-regulated in VSMCs in the aorta and the lung and in this instance IL11 expression is likely due to increased TGFβ activity, which defines Marfan syndrome." (PMID 38054591, 2023). "Consequently, in a Marfan syndrome (MFS) model, the mRNA and protein expression of IL-11 was overexpressed in the aorta (especially in the aortic root and ascending aorta), and IL-11RA were overexpressed on aortic media VSMCs and adventitial fibroblasts." (PMID 37304948, 2023). "Whether targeting IL11 in rare human genetic disease offers an approach for disease mitigation, beyond gene therapy, is unknown but POC in animal models of Alport and Marfan syndrome suggests this premise may be worth testing in clinical trials." (PMID 38054591, 2023).
metabolic syndrome (3 papers, 2017 to 2023). A cluster of metabolic risk factors for CARDIOVASCULAR DISEASES and TYPE 2 DIABETES MELLITUS. "In contrast, the multifunctional cytokine IL-11 acts as an effective inhibitor of adipogenesis, one of the factors of the metabolic syndrome." (PMID 28763032, 2017).
mucositis (3 papers, 2010 to 2023). Mucositis is inflammation and damage of the mucous membranes lining the mouth and other parts of the gastrointestinal (GI) tract. "We examined the time and severity of oral mucositis, severity and duration of associated pain, healing time of mucositis, effects of OM on eating, and levels of T-cell subset indicators before and after treatment to evaluate the effects of IL-11 treatment." (PMID 37438702, 2023). "There remains, however, a huge gap in the knowledge to recognise whether anti-inflammatory cytokines such as IL-4, IL-10, IL-11, and IL-1ra are essential tools in downregulating the inflammatory response associated with mucositis." (PMID 22973511, 2012). "Although IL-11 is well researched in a number of different inflammatory conditions, current literature lacks to understand the direct mechanism of IL-11 on the intestinal epithelium relating to ameliorating chemotherapy-induced mucositis." (PMID 22973511, 2012). "However, further research is needed on the mechanism of IL-11 in treating mucositis." (PMID 37438702, 2023).
oral mucositis (3 papers, 2010 to 2023). Inflammation of the mucous membranes of any of the structures in the mouth. "This study aimed to investigate the clinical effects of recombinant human interleukin-11 (rhIL-11) gargle on preventing and treating oral mucositis (OM) after chemotherapy for acute leukemia." (PMID 37438702, 2023). "Various potential therapeutics have been assessed clinically for oral mucositis including recombinant IL-11, granulocyte-macrophage colony-stimulating factor (GM-CSF), G-CSF and TGF-β3." (PMID 20602770, 2010).
oral squamous cell carcinoma (3 papers, 2021 to 2025). "The inflammatory cytokine interleukin-11 (IL-11)/gp130 can upregulate MMP-13 expression in oral squamous cell carcinoma (OSCC) through the activation of the PI3K/Akt and AP-1 signaling pathways, thereby promoting cancer cell migration." (PMID 40282437, 2025). "The oral squamous cell carcinoma cell HSC2, when exposed to milk, increased ID1 and ID3 genes but failed to increase IL11 (data not shown)." (PMID 34789212, 2021).
renal carcinoma (3 papers, 2016 to 2017). A carcinoma arising from the epithelium of the renal parenchyma or the renal pelvis. "IL-11 overexpression attenuated the effects of KRT8 knockdown on renal cancer cell migration and invasion." (PMID 29100303, 2017). "Similar effects were seen in a distinct renal cancer cell line, 786-0, however, in HK2 cells (normal kidney) SERPINE1 and IL-11 were downregulated along with EDN2, while BIRC3 was upregulated." (PMID 27384883, 2016). "To further explore whether KRT8 promotes renal cancer cell migration and invasion through IL-11/STAT3, we overexpressed or knocked down IL-11 to conduct functional studies in renal cancer cells." (PMID 29100303, 2017). "Furthermore, high expression of interleukin-11 correlated with poor prognosis in clear-cell renal carcinoma, highlighting the clinical relevance of an early detection of IL-11 and CCL20 in renal carcinoma patients." (PMID 27322553, 2016).